NLRP3 (NLR family pyrin domain containing 3)
Diseases named in the same sentence as NLRP3 in open-access papers (continued):
Sharing a sentence is not in itself a finding about the gene and the disease.
COVID-19 (continued). "Activation of NLRP3 inflammasome is associated with disease severity in COVID-19 patients." (PMID 33923537, 2021). "Given that the suppression of NLRP3 inflammasome by estrogen impairs the immune response against the virus and increases the risk of infection, this somehow explains that the majority of asymptomatic COVID-19 patients are females." (PMID 34150848, 2021). "In COVID-19 patients, NLRP3 has been shown to be strictly associated with disease severity." (PMID 34471404, 2021). "Cytokine storm is associated with the severity and mortality of COVID-19 patients, which may be regulated by a key inflammation regulator known as the NLRP3 inflammasome." (PMID 34512335, 2021). "Among the NLRPs, an association of the NLRP3 inflammasome with COVID-19 is reported." (PMID 33923537, 2021). "The massive release of TNF-α, IFN-γ, IL-1β, IL-8, MCP-1, and IP-10 seen in acute phase of COVID-19 patients may probably be linked to pyroptosis, especially in lymphocytes through the NLRP3 inflammasome activation." (PMID 33193349, 2020). "In sum, COVID-19 causes an array of disease manifestations, the most severe of which is mediated by a massive inflammatory response that appears to occur through stimulation of the NLRP3 inflammasome." (PMID 32655582, 2020). "Some authors postulate that the NOD-like receptor family pyrin domain containing 3 (NLRP3), the major protein component of the inflammasome, may play a central role in the predisposition to the cytokine storm observed in certain COVID-19 patients." (PMID 33003552, 2020). "Similarly, IL-1β antagonists or NLRP3 inflammasome inhibitors may be tested in COVID-19-associated coagulopathy to evaluate their ability to reduce thrombo-inflammatory complications." (PMID 41311551, 2025). "In addition, danger signals, such as calcitonin, which have been recently associated with the severity of COVID-19, are known to activate or release NLRP3 inflammasomes as a result of their activation, and may cause prolapse." (PMID 38399989, 2024). "Furthermore, examination of the whole blood transcriptome in COVID-19 patients has revealed that the dysregulated immune system in COVID-19 is characterized by highly specific neutrophil activation-associated signatures, with an increase in immature neutrophils with NLRP3 inflammasome activation." (PMID 36830874, 2023). "Moreover, NLRP3 inflammasome activation and hyperinflammation is associated with COVID-19 severity, and Pan and collaborators demonstrated that SARS-CoV-2 nucleocapsid protein can directly interact with NLRP3 to promote the assembly and activation of NLRP3 inflammasome." (PMID 37711609, 2023). "Moreover, interleukin-mediated modulation of phosphokinases and phosphatases, NOD-like receptor thermal protein domain associated protein 3 (NLRP3) inflammasome-mediated inflammation and pathological accumulation of amyloid-β are associated with COVID-19 related neurological disorder." (PMID 37889436, 2023). "Indeed, the recent description of NLRP3 activity contributing to SARS‐CoV‐2 disease and potential markers of poor disease outcome, further highlights the delicate balance of inflammasome activation required." (PMID 37360982, 2023). "Our results, therefore, suggest that NLRP3-inflammasome-related miRNAs and their regulated cytokines or receptors could represent a novel diagnostic or therapeutic target in pulmonary sequelae of COVID-19-related ARDS." (PMID 37685844, 2023). "Once activated, NLRP3 inflammasome causes the release of several proinflammatory cytokines, including IL-6 and IL-1β, which have been reported to have a key role in the pathogenesis of acute lung injury, included COVID-19, affecting type II alveolar epithelial cells ACE2 expression." (PMID 35336077, 2022). "Therefore, key compotents (such as NLRP3 inflammasome, caspase-1,-4,-8,-11 and so on) in signaling pathways associated with pyroptosis might be promising drug targets for severe COVID-19 treatment." (PMID 36248872, 2022).
COVID-19 (continued). "Although physiological NLRP3 inflammasome activation is important in innate immunity, its pathophysiological activation is implicated in many chronic inflammatory diseases, including cancers and cardiovascular diseases, and in triggering cytokine storms in COVID-19." (PMID 35563697, 2022). "The inflammatory response caused by NLRP3 inflammasome activation under particular cardiovascular conditions results in hyperinflammatory responses by intensifying the inflammatory response induced by COVID-19 or by modulating the angiotensin-converting enzyme 2 (ACE2)/angiotensin signaling pathway." (PMID 33923537, 2021). "The results showed active NLRP3 in the samples which was associated with caspase 1, IL-18 activity, disease severity and poor clinical outcomes, suggesting that NLRP3 could serve as a therapeutic target for COVID-19." (PMID 34123871, 2021). "Given that elevated concentrations of IL-1β and IL-6 are associated with adverse clinical outcomes in COVID-19,9, 10 targeting the NLRP3 inflammasome (which is responsible for the maturation and secretion of IL-1β) might reduce related complications in patients at risk of cytokine activation." (PMID 34051877, 2021). "Hence, for male, elderly, obese and high-risk COVID-19 patients with NLRP3 inflammasome overactivation, drugs that target NLRP3 inflammasome may be used to prevent disease progression from mild to severe." (PMID 34150848, 2021). "Another cell-death pathway prominent in peripheral blood mononuclear cells in patients with COVID-19 is pyroptosis, characterized by NLRP3 activation." (PMID 41550884, 2026). "The protein 3a of SARS-CoV-2 can activate NLRP3 in macrophages in patients with COVID-19 complicated by ARDS." (PMID 41550884, 2026). "Like NLRs, the NOD-like receptor family pyrin containing 3 (NLRP3) inflammasome can be activated by viral proteins such as ORF3a in COVID-19." (PMID 40371107, 2025). "Multiple lines of evidence in COVID-19 show NLRP3 priming/activation in circulating leukocytes and tissues, with increased IL-1β correlating with severity and hypercoagulability." (PMID 41010381, 2025). "Post-mortem analysis of COVID-19 patients has revealed persistent NLRP3 inflammasome activation in various tissues and PMN from peripheral blood." (PMID 41009326, 2025). "In the context of COVID-19, NLRP3 inflammasome activation has been observed in patients and associated with pyroptosis of infected monocytes." (PMID 40788382, 2025). "IPF showed CTSK overexpression in AT2 cells, COPD exhibited NLRP3 activation, and COVID-19 displayed viral defense gene SAMD9 upregulation." (PMID 41122970, 2025). "This aligns with prior research showing that ionizable lipids, such as those used in COVID-19 vaccines, can trigger strong immune responses, including neutrophil infiltration and activation of inflammatory pathways like NF-κB and NLRP3." (PMID 41459744, 2025). "Patients with metabolic disorders develop severe COVID-19 with exacerbated metabolic inflammation partially regulated by NLRP3." (PMID 40788382, 2025). "This study, based on post-mortem lung biopsies of obese individuals who died from COVID-19 or other chronic conditions, aims to evaluate the activation of the NLRP3 inflammasome pathway." (PMID 40004007, 2025). "This excessive stimulation is directly related to the severity of COVID-19, as shown by elevated NLRP3 levels in critically ill patients." (PMID 40497938, 2025). "The severity of COVID-19 with tissue damage and relevant cytokine storm has been correlated with NLRP3 inflammasome activation." (PMID 41009326, 2025). "The activation of NF-κB, elevation of angiotensin II, and oxidative stress in COVID-19 also stimulate the intracellular NLR family pyrin domain containing 3 (NLRP3) inflammasome." (PMID 40141299, 2025).
COVID-19 (continued). "Benefits resulting from this senolytic action is suggested by observations showing that quercetin decreases the severity of COVID-19-induced inflammation and expedites recovery, and that apigenin deactivates the NLRP3 inflammasome." (PMID 41437993, 2025). "We concluded that COVID-19 activates the NLRP3 inflammasome pathway, possibly leading to pyroptotic cell death mediated by caspase-1." (PMID 40004007, 2025). "This patient initially presented with localized periorbital inflammation, which progressed to systemic disease following her third dose of the COVID-19 vaccine—a known trigger for dysregulated NLRP3 activation." (PMID 40927711, 2025). "Periodontitis and COVID-19 share several common inflammatory pathways, such as the NLRP3/IL-1β and IL-6 signaling pathway." (PMID 40406515, 2025). "To date, clinical trials testing NLRP3 inhibitors in COVID-19 patients have been inconclusive, only showing subtle changes in mortality and not being successful in improving APACHE II scores compared to treatment with standard-of-care alone." (PMID 40016339, 2025). "Post-mortem analysis of COVID-19 patients has revealed persistent NLRP3 inflammasome activation in various tissues and PMNs from peripheral blood." (PMID 40406515, 2025). "Recent evidence indicates that neutrophils from patients with severe COVID-19 also exhibit enhanced NLRP3 activation, further amplified by type I interferon signaling." (PMID 40959087, 2025). "Suppressing the NLRP3 inflammasome reduces COVID-19-like pathology, indicating that NLRP3 inflammasome activation plays an important role in the pathogenesis of SARS-CoV-2 infection." (PMID 40307577, 2025). "The NLRP3 inflammasome plays a key role in the cytokine storm observed during both COVID-19 and periodontitis, since its activation induces the synthesis and release of proinflammatory cytokines, which causes tissue damage and inflammation in both diseases." (PMID 41009326, 2025). "Lung tissues, peripheral blood mononuclear cells and monocytes of severe COVID-19 patients displayed increased NLRP3 activation and increased levels of IL-1β." (PMID 38748756, 2024). "COVID-19-associated inflammation can activate the NOD-like receptor family, pyrin domain-containing 3 (NLRP3) inflammasome, further contributing to severe disease outcomes in cancer patients." (PMID 39156288, 2024). "Other drugs targeting the NLRP3 pathway have been investigated in clinical trials or considered for repurposing to manage cytokine storms in COVID-19." (PMID 38251382, 2024). "In severe COVID-19 cases, reactive oxygen species (ROS) arising from inflammation, and infiltration activates of NLRP3, which is one of the most significant innate immune components." (PMID 38585461, 2024). "The pathogenesis of COVID-19-related neurological complications, characterized by cytokine storms and NLRP3 inflammasome activation, necessitates further research into their mechanisms." (PMID 38543856, 2024). "Suppression of type I IFN signaling pathway and exacerbation of NLRP3 inflammasome activation enhance the hyperinflammation and severity of COVID-19." (PMID 38748756, 2024). "As NLRP3 inhibition reduced COVID-19–like hyperinflammation and pathology in preclinical models, this has potential to treat severe SARS-CoV-2 complications." (PMID 38388172, 2024). "Our recent inspections of the lungs of patients with COVID-19 revealed a significantly high expression of NLRP3 inflammasome along the around the vessel walls (endothelial layer) as compared to in lungs from non-COVID-19 affected individuals." (PMID 38771750, 2024). "In the context of COVID-19, NLRP3 inflammasome activation can drive prolonged and excessive inflammation, contributing to cytokine storm in severe cases and potentially leading to long-term immune dysregulation." (PMID 39720706, 2024). "In this study, we assessed lung autopsies of 47 fatal cases of COVID-19 and found a significant activation of the NLRP3 inflammasome in the lungs of patients." (PMID 38838044, 2024).
COVID-19 (continued). "Here we assessed the endothelial inflammation (i.e., the pro-inflammatory phenotype of ECs) by monitoring ICAM-1, NLRP3 and P-selectin in HPMVECs in an in vitro COVID-19 model." (PMID 38771750, 2024). "Despite the widespread attention given to NLRP3 as a potential target for COVID-19 treatment, inhibitors targeting this pathway are still in early-stage research." (PMID 38399989, 2024). "Future investigations should aim to explore the clinical viability, efficacy, and mechanisms of NLRP3 inhibitors in curbing the inflammatory process of COVID-19." (PMID 38399989, 2024). "It is understood that several inflammasomes are activated, but NLRP3 is highlighted for its contribution to organ dysfunction and disease severity during COVID-19." (PMID 38391754, 2024). "As a conclusion, the results of this study support a role for the NLRP3-inflammasome activation and IL-1 in the immunopathogenesis of COVID-19." (PMID 39882243, 2024). "Diacerein-treated COVID-19 patients presented a smaller area under the curve for NLRP3, caspase-1 and GSDM-D measured on days 2, 5, and 10 after hospitalization compared to those receiving a placebo (p < 0.05)." (PMID 39434905, 2024). "HPMVEC exposed to normal serum showed very minimal ICAM-1 and NLRP3 subunit expression (green fluorescence arising from secondary antibody) as compared to cells treated with COVID-19 serum." (PMID 38771750, 2024). "NLRP3 is the most extensively studied inflammasome in COVID-19 owing to its critical role in mediating infection-induced inflammation." (PMID 38612539, 2024). "To assess the consequences of NLRP3-inflammasome and caspase-1 activation in COVID-19 patients, we measured the levels of IL-1β, IL-1Ra and IL-6 in both BALF and serum of C-ARDS or NC-ARDS patients and in control subjects." (PMID 39882243, 2024). "It serves as a valuable reference for future clinical approaches in addressing COVID-19 by targeting NLRP3, thus providing potential avenues for therapeutic intervention." (PMID 38399989, 2024). "This protein mediates the secretion of IL-1β, requiring K+ outflow and mitochondrial ROS production, elucidating the potential of the NLRP3 inflammasome as a molecular target for COVID-19 treatment." (PMID 38399989, 2024). "During COVID-19, strong activation of the NLRP3-inflammasome and caspase-1 is induced with subsequent release of IL-1β and IL-18, although these cytokines remain difficult to detect in patient’s blood." (PMID 39882243, 2024). "The log2 fold change of differentially expressed genes (DEGs) in monocytes within PBMCs of severe and mild COVID-19 patients confirmed the log2 fold change observed in NLRP3 (0.22), CASP-1 (0.29) and IL-1β (1.16) during severe stages of SARS-CoV-2 infection." (PMID 38748756, 2024). "COVID-19 also activated the inflammasome and NLRP3, potentially providing another immunopathogenic correlation between MS and COVID-19." (PMID 38887342, 2024). "The RNAseq data on whole blood (EGAS00001004503) of 10 controls, 20 severe and 19 mild COVID-19 patients showed log2 fold change in NLRP3 (1.25), CASP-1 (1.21) and IL-1β (1.38) in severely infected patients only." (PMID 38748756, 2024). "By synthesizing existing studies, this paper offers insights into NLRP3 as a therapeutic target, elucidating the interplay between COVID-19 and its pathophysiology." (PMID 38399989, 2024). "Colchicine is a well-established and safe treatment for pericarditis and appears to be the treatment of choice in COVID-19 cases due to its action on NLRP3 inflammasomes and cytokine release." (PMID 38989350, 2024). "Immunohistochemistry indicated higher levels of NLRP3 in post-mortem tissues from COVID-19 patients compared to controls, and there were correlations with Casp1p20 and IL-18 and disease severity [63•]." (PMID 38221578, 2024).
COVID-19 (continued). "Our results confirm the contribution of the NLRP3 inflammasome pathway to COVID-19 severity and the ability of VitD3 to attenuate hyperinflammation via downregulating the NLRP3 inflammasome pathway." (PMID 38748756, 2024). "NLRP3 inflammasome activation has been observed in monocytes of patients with COVID-19, but the mechanism and consequences of inflammasome activation require further investigation." (PMID 39240187, 2024). "Neuroinflammation, characterized by cytokine storms and NLRP3 inflammasome activation, has appeared as a significant factor in the pathogenesis of COVID-19-related neurological complications." (PMID 38543856, 2024). "We here report the ability of VitD3 to downregulate the NLRP3-inflammsome pathway in severe COVID-19 patients." (PMID 38748756, 2024). "Colchicine, an NLRP3 inflammasome inhibitor, has been found to improve outcomes in COVID-19 patients." (PMID 39113913, 2024). "ORF3a-mediated signaling pathways involve key cellular regulators such as NLRP3, NF-κB, and related cytokines (TNFα and IL-6), all well-known druggable cellular targets relevant to COVID-19." (PMID 38251382, 2024). "Clinically, COVID-19 patients had higher concentrations of Casp1p20 and IL-18 in their serum and NLRP3 activation in their peripheral blood mononuclear cells [63•]." (PMID 38221578, 2024). "The progression of COVID-19 involves intricate immune responses, notably the activation of NLRP3 inflammasomes." (PMID 38399989, 2024). "This review investigates the potential correlation between NLRP3 inflammasomes and COVID-19, exploring the cellular and molecular mechanisms through which SARS-CoV-2 triggers their activation." (PMID 38399989, 2024). "In particular, a relationship between COVID-19 aggravation and rs10754558 NLRP3, rs6509365 CARD8, rs2043211 CARD8, rs16944 IL1B, and rs755622 MIF have been described." (PMID 38612539, 2024). "The broad-spectrum and specific inhibitory effects of CDN on NLRP3 inflammasome make it an attractive therapeutic agent in CS-induced COVID-19 ARDS." (PMID 39051370, 2024). "Circulatory exosomes obtained from patients in severe COVID-19 serve as an amplification hub for NLRP3 priming signals under this condition." (PMID 37515138, 2023). "Several host targets (such as neutrophils, monocytes/macrophages and lymphocytes), which have been associated with the pathogenesis of SARS-CoV-2 infection, exhibited NLRP3 inflammasome activation during severe COVID-19." (PMID 37920468, 2023). "Studies have shown that the NLRP3 inflammasome is active and there are high levels of IL-1β and IL-18 in COVID-19 patients." (PMID 37631016, 2023). "Herc6 deficiency ameliorated NLRP3-dependent inflammation and ARDS (a direct cause death in patients with COVID-19) in vivo." (PMID 37651190, 2023). "According to postmortem findings, tissues and peripheral blood mononuclear cells from COVID-19-infected individuals who died still had active NLRP3 inflammasomes." (PMID 36769328, 2023). "Myeloid cells isolated from COVID-19 patients showed heterogeneous NLRP3 inflammasome activation potentials." (PMID 37251383, 2023). "Alterations in the renin–angiotensin system (RAS), with consequent activation of the NLRP3 (NOD-like receptor 3) inflammasome, is the probable reason why hypertensive patients are more susceptible to severe forms of COVID-19." (PMID 37371071, 2023). "Pyroptosis, a P2X7R- and NLRP3-dependent inflammatory cell death, is suggested to contribute to COVID-19 disease severity." (PMID 37215142, 2023). "Abnormal activation of the NLRP3 inflammasome in COVID-19 is involved in the pathogenesis of cytokine storm, acute respiratory distress syndrome (ARDS), and acute lung inflammation (ALI), as well as pathological multi-organ damage." (PMID 37376562, 2023). "Compared with non-COVID-19 subjects, the expression of NLRP3 and caspase-1 was increased along the vascular wall in COVID-19 ARDS cases, suggesting the activation of NLRP3 inflammasome in vessel wall." (PMID 37251383, 2023).